STAT4 (signal transducer and activator of transcription 4)
Diseases named in the same sentence as STAT4 in open-access papers (continued):
Sharing a sentence is not in itself a finding about the gene and the disease.
autoimmune hepatitis (3 papers, 2013 to 2022). Hepatitis caused by autoantibodies. "We therefore investigated the influence of STAT4 polymorphisms on the susceptibility and phenotype of type-1 autoimmune hepatitis in a Japanese National Hospital Organization (NHO) AIH multicenter cohort study." (PMID 23990947, 2013). "BBR activated the AMPK pathway on concanavalin-A-induced autoimmune hepatitis (AIH) in mice and affected the JAK/STAT signaling pathway by the reduction in STAT1 and STAT4 phosphorylation, leading to suppressed Th1 differentiation and function in different animal models." (PMID 35631330, 2022).
autoimmune myocarditis (3 papers, 2020 to 2025). Autoimmune myocarditis is an autoimmune disease that affects the heart. "Aberrant STAT4 expression has been documented in autoimmune myocarditis, and the IL-12-STAT4 signaling axis has been implicated in disease pathogenesis." (PMID 41222876, 2025). "An attractive study disclosed that miR-141-3p lightened inflammation and triggered an anti-inflammatory effect in experimental autoimmune myocarditis mice through suppressing STAT4 expression." (PMID 32850524, 2020).
celiac disease (3 papers, 2011 to 2025). An autoimmune genetic disorder with an unknown pattern of inheritance that primarily affects the digestive tract. "Lastly, four of the nine TPOA associated SNPs (in SH2B3, CTLA4, BACH2 and UBASH3A) have also been associated with celiac disease (but not the SNPs in RASGRP1, STAT4, PTPN22, IL2 and FCRL3)." (PMID 21829393, 2011).
chronic hepatitis B (3 papers, 2019 to 2024). "Validation with all the genetic models revealed that rs7574865 polymorphism of STAT4 gene was closely associated with chronic HBV infection (PA<0.01) and chronic hepatitis B (CHB)-related HCC (PA<0.05)." (PMID 31160486, 2019).
experimental autoimmune encephalomyelitis (3 papers, 2015 to 2022). An autoimmune demyelinating disease of the central nervous system that is produced experimentally in animals by the injection of homogenized brain or spinal cord in Freund's adjuvant. "Additionally, BE has an immunomodulatory effect and is reported to reduce signal transducer and activator of transcription 4 (STAT4) and IFN-γ expression, specifically in experimental autoimmune encephalomyelitis." (PMID 35958317, 2022).
Graves disease (3 papers, 2014 to 2021). Graves' disease is an autoimmune disorder that leads to overactivity of the thyroid gland (hyperthyroidism).It is caused by an abnormal immune system response that causes the thyroid gland to produce too much thyroid hormones. "Of note, STAT4−/− mice developed equivalent susceptibility in mouse models of myasthenia gravis and Graves disease, both of which are mediated by Ab-dependent mechanisms." (PMID 33446493, 2021). "STAT4 rs7574865 polymorphism was significantly associated both with Graves’ disease (GD) and Hashimoto’s thyroiditis (HT) susceptibility." (PMID 30666271, 2018). "The aim of this study was to explore the association of STAT4 polymorphism with Graves’ disease (GD) and Hashimoto’s thyroiditis (HT)." (PMID 25019342, 2014).
hypothyroidism (3 papers, 2019 to 2023). Abnormally low levels of thyroid hormone.
IgA nephropathy (3 papers, 2010 to 2023). "Thus, one might speculate that susceptibility to IgA nephropathy may be due to common variations in IRF5, TRAF1-C5 and STAT4 genes." (PMID 20479942, 2010).
leprosy (3 papers, 2017 to 2024). Leprosy is a chronic infectious disease affecting primarily the skin and peripheral nervous system. "This study has been done to correlate differential Th1/Th2 cell mediated immune responses observed in leprosy with known T cell transcription factors (STAT-4, STAT-6 and CREB) ex vivo along with the effect of M. leprae antigens (MLSA, WCL and PGL-1) on the modulation of these transcription factors." (PMID 30642265, 2019). "One very recent study showed immunostaining of STAT4 in the skin of patients with leprosy." (PMID 28107529, 2017). "This study shows differential expression of T cell transcription factor STAT-4, STAT-6 and CREB in leprosy patients and healthy individuals correlating with Th1 and Th2 cytokine expression." (PMID 30642265, 2019). "In the present study, we studied the effect of M. leprae antigens on transcription factors STAT-4, STAT-6 and CREB and their correlation with Th1/Th2 cell mediated immune responses in leprosy." (PMID 30642265, 2019). "Therefore, in the present study we have studied M. leprae antigens mediated Th1/Th2 specific T cell transcription factors STAT-4, STAT-6, and CREB activation and cytokine production in leprosy patients and healthy individuals." (PMID 30642265, 2019).
leukemia (3 papers, 2017 to 2023). A malignant (clonal) hematologic disorder, involving hematopoietic stem cells and characterized by the presence of primitive or atypical myeloid or lymphoid cells in the bone marrow and the blood. "Here, we expand the function of miR-141/200c to a potential regulation of STAT4, as well as presenting data on accelerated proliferation and diminished stress-induced cell death upon miR-141/200c upregulation in T-cell lymphoma/leukemia models." (PMID 37173993, 2023). "Consistently, STAT4 expression decreases in leukemia cells treated with shRNA against GATA3, which was also confirmed in previous reports." (PMID 28415601, 2017). "Furthermore, we found strong activation of Hif1α, Stat1 and Stat4 pathways in Gr-1+ population upon DS-5272 treatment, indicating the enhanced inflammatory signaling in the relatively differentiated leukemia cells in agreement with the RNA-seq data above." (PMID 31653912, 2019).
liver fibrosis (3 papers, 2015 to 2023). "Numerous findings suggest a protective role of IL-12/STAT4 in hepatic fibrosis, with key roles in tissue inflammation, fibrogenesis, and viral defense." (PMID 36671504, 2023). "The roles of STAT4 in hepatic fibrosis are also bidirectional." (PMID 36671504, 2023). "These previous findings enhance the biological plausibility that this SNP in STAT4 may play an important role in the liver fibrosis progression, although the molecular mechanism remains uncertain and further functional studies are required." (PMID 26538132, 2015).
lymph node metastasis (3 papers, 2019 to 2025). "Remarkably, we observed lymph node metastasis in 80% and lung metastasis in 60% of tumor bearing Stat4−/− mice compared with WT who displayed incidences of only 20% for both draining lymph node and lung metastasis." (PMID 32010142, 2019). "The G allele of STAT4 rs10181656 is statistically significantly more frequent in LSCC patients without lymph node metastases compared to the control group (41.1% vs. 21.4%, p < 0.001)." (PMID 39337665, 2024). "While studies on STAT4 and STAT6 are limited, both have been implicated in immune regulation and tumor progression, with STAT4 overexpressed in squamous cell carcinoma and cervical adenocarcinoma, especially with lymph node metastasis (Gutiérrez-Hoya and Soto-Cruz, 2020)." (PMID 40667502, 2025). "Binomial logistic regression analysis of the selected STAT4 SNVs in LSCC patients with neck lymph node metastases and controls did not reveal any statistically significant results." (PMID 39337665, 2024).
metastatic tumor (3 papers, 2019 to 2024). "The T allele of STAT4 rs7574865 is statistically significantly more common in LSCC patients with non-metastatic tumor compared to the control group (29% vs. 21.3%, p = 0.002)." (PMID 39337665, 2024). "However, total IL-17 expression at primary and metastatic tumor sites, as shown by IL-17 mRNA transcripts were similar for both WT and STAT4 deficient tumor bearing mice, suggesting that IL-17 expression by non-T cells, which is a potentially STAT4-independent process that may be playing a role." (PMID 32010142, 2019). "Transcripts of Il-1b, a member of the IL-1 family which has been shown to be a prognostic for distant metastasis in HNSCC, was also significantly elevated in metastatic tumor bearing Stat4−/−mice." (PMID 32010142, 2019). "The increased rate of metastasis in tumor bearing Stat4−/− mice led us to examine transcriptional expression of HNSCC biomarkers at the primary and metastatic tumor sites (lymph node)." (PMID 32010142, 2019).
Oral ulcer (3 papers, 2008 to 2017). Erosion of the mucous mebrane of the mouth with local excavation of the surface, resulting from the sloughing of inflammatory necrotic tissue. "In contrast, STAT4 was less strongly associated with oral ulcers, a manifestation associated with milder disease." (PMID 18516230, 2008). "There is also strong evidence that the STAT4 risk allele is less frequent in SLE with oral ulcers, MAF = 28.8%, which is generally associated with milder disease." (PMID 18516230, 2008). "They include the concordances we have already signalled relating STAT4 with earlier disease onset or oral ulcers." (PMID 23049788, 2012). "For example, the rs7574865 SNP in STAT4 has been associated with a severe SLE phenotype defined by nephritis, age at diagnosis <30 years old, immunologic disorder (and, specifically, double-stranded DNA autoantibodies) and absence of oral ulcers." (PMID 23049788, 2012).
osteoporosis (3 papers, 2023 to 2024). A condition of reduced bone mass, with decreased cortical thickness and a decrease in the number and size of the trabeculae of cancellous bone (but normal chemical composition), resulting in increased fracture incidence. "Mendelian randomization analysis found that there was a causal relationship between STAT4 as a risk factor and osteoporosis in general (p < 0.05)." (PMID 37949959, 2023). "In addition, the results of RT-qPCR and Elisa experiments verified that the expression of STAT4 was consistent with the previous analysis, and a significant causal relationship between IL-2 and STAT4 SNPs and osteoporosis was found by Mendelian randomization." (PMID 37949959, 2023). "Meanwhile, our results also showed a significant negative correlation between STAT and activated DCs, suggesting that STAT4 may promote the development of osteoporosis through the loss of DCs." (PMID 37949959, 2023). "In addition, we collected human blood samples from the hospital for RT-qPCR and Elisa experiments to validate hub genes, and analyzed the causal relationship between inflammatory cytokines, STAT4, and osteoporosis by Mendelian randomization." (PMID 37949959, 2023). "Bayesian co-localization analysis revealed co-localization of HBV infection and osteoporosis on STAT4 at rs11889341based on East Asian GWAS data." (PMID 39911237, 2024). "Although our study proposed the Palbociclib/miR-141-3p/STAT4 axis for the first time and provided new insight into the mechanism of oxidative stress in osteoporosis, there are limitations that need to be considered." (PMID 37949959, 2023). "In conclusion, our study proposed the Palbociclib/miR-141-3p/STAT4 axis for the first time and provided a new perspective on the mechanism of oxidative stress in osteoporosis." (PMID 37949959, 2023). "Verified by RT-qPCR and Elisa experiments, we found that the STAT4 gene was significantly up-regulated in the osteoporosis group." (PMID 37949959, 2023). "In this study, we proposed the Palbociclib/miR-141-3p/STAT4 axis for the first time and provided new insights into the mechanism of oxidative stress in osteoporosis." (PMID 37949959, 2023). "However, further research is needed to understand the molecular mechanism by which STAT4 regulates the development of osteoporosis." (PMID 37949959, 2023). "Our results confirmed that STAT4 may be a novel biomarker for the prevention and treatment of osteoporosis." (PMID 37949959, 2023). "Finally, through miRNA-mRNA network and drug sensitivity analysis, we analyzed to get Palbociclib/miR-141-3p/STAT4 axis, which can be used for the prevention and treatment of osteoporosis." (PMID 37949959, 2023). "Finally, we constructed a network to obtain the miR-141-3p/STAT4 axis and obtained a new drug Palbociclib for the prevention and treatment of osteoporosis through drug sensitivity analysis." (PMID 37949959, 2023). "Importantly, our results combined with previous studies hinted that STAT4 may be a pivotal molecule in the process of increasing the prevalence of osteoporosis under HBV infection." (PMID 39911237, 2024). "However, this is still our speculation and additional researches are required to ascertain the molecular mechanism by which STAT4 regulated the process that HBV infection contributed to the development of osteoporosis." (PMID 39911237, 2024). "Therefore, we speculate that STAT4 may be a key molecule mediating the causal relationship between HBV infection and osteoporosis." (PMID 39911237, 2024). "Thus, the low expression of miR-141-3p in OP might promote the inflammatory response, this is the first reported relationship between miR-141-3p and STAT4 in osteoporosis." (PMID 37949959, 2023). "Furthermore, single-cell analysis showed a negative correlation between STAT4 and activated dendritic cells (DCs), which differentiate into osteoclasts and promote bone resorption, further linking STAT4 to osteoporosis." (PMID 39911237, 2024).
osteoporosis (continued). "However, the current study suggested that STAT4 may be a novel biomarker for the prevention and treatment of HBV and osteoporosis, which is in agreement with our findings." (PMID 39911237, 2024). "In summary, although not many studies have been conducted on the effect of STAT4 in HBV and osteoporosis, especially the relationship between STAT4 and osteoporosis." (PMID 39911237, 2024).
prostate tumor (3 papers, 2010 to 2023). "To confirm this observation, we adoptively transferred Stat4-K350R– or Stat4-WT–transduced macrophages into the adjacent sites of prostate tumors." (PMID 36626227, 2023). "Collectively, these data indicate that murine prostate tumor cells induce a partial activation state in iNKT cells characterized by STAT4 phosphorylation blockade." (PMID 20593019, 2010). "However, despite inducing up-regulation of these activation markers and, hence, delivering positive signals, prostate tumor cells inhibited the IL-12-induced STAT4 phosphorylation in a cell-cell contact dependent but CD1d-independent manner." (PMID 20593019, 2010).
pulmonary fibrosis (3 papers, 2013 to 2024). Chronic progressive interstitial lung disorder characterized by the replacement of the lung tissue by connective tissue, leading to progressive dyspnea, respiratory failure, or right heart failure. "By contrast, we report the novel finding that the STAT4 rs7574865 T allele may be protective against the development of lung fibrosis in SSc patients." (PMID 31916109, 2020). "In a bleomycin-induced pulmonary fibrosis mice model, IL-35 activated STAT1 and STAT4, which in turn suppressed DNA enrichment of STAT3 and inhibited the fibrosis process." (PMID 38641226, 2024).
rectal cancer (3 papers, 2016 to 2023). A primary or metastatic malignant neoplasm that affects the rectum. "Recent reports suggested that genetic variations in STAT4 in rectal cancer are associated with rectal cancer survival." (PMID 30987235, 2019). "A potential role of the STAT4 molecule in cancer has also been suggested based on an association of rectal cancer and genetic variations in STAT4." (PMID 26938566, 2016).
Salmonella Infections (3 papers, 2016 to 2020). Infections with bacteria of the genus SALMONELLA. "In humans, STAT4 variants have been linked to increased risk for invasive Salmonella infection." (PMID 32834002, 2020). "Herein, we found a reduced IFN-γ mRNA expression during the establishment of the persistent Salmonella infection and an increased phosphorylation of STAT1 and dephosphorylation of STAT4." (PMID 27472318, 2016). "Furthermore, the ratio between STAT1 and STAT4 are crucial for IFN-γ production during viral and Salmonella infections." (PMID 27472318, 2016). "There is no established role for STAT4 in monocytes during Salmonella infection." (PMID 29523850, 2018).
Sepsis (3 papers, 2022 to 2024). Sepsis is defined as life-threatening organ dysfunction caused by a dysregulated host response to infection. "Subsequently, we identified module and hub genes (CD4 and STAT4) via construction of a sepsis immune-related PPI network." (PMID 37620751, 2023). "The dysregulation expression of STAT4 genes in monocytes of sepsis patients may inhibit its therapeutic potential." (PMID 37620751, 2023). "Furthermore, CD4 and STAT4 had higher degrees in the PPI network and have been reported participate in immune mechanisms underlying sepsis, which indicated their important regulate roles in sepsis immune processes." (PMID 37620751, 2023). "Recently, several studies indicated that CD4 and STAT4 could be participated in the development of sepsis." (PMID 37620751, 2023). "The volcano plot and heatmap indicated that JAK3, CHMP5 and IFNAR1 were upregulated while CASP8, VDAC2, FASLG, JAK1, STAT4 and BCL2 were downregulated in sepsis." (PMID 38894720, 2024). "Baicalin regulated multiple members of the STAT family, including STAT1, STAT3, STAT4, and STAT5, for treating T2D-induced liver tumor, sepsis, and myocardial ischemia reperfusion injury." (PMID 36324680, 2022).
squamous cell carcinoma (3 papers, 2020 to 2025). A carcinoma arising from squamous epithelial cells. "The role of STAT4 in cervical cancer has been poorly studied and understood; however, a higher expression of STAT4 has been reported in histological sections of patients with squamous cell carcinoma and adenocarcinomas compared to non-cancerous lesions." (PMID 37372319, 2023).
age-related macular degeneration (2 papers, 2023 to 2024). Age-related loss of vision in the central portion of the retina (macula), secondary to retinal degeneration. "STAT4 protein is involved in the pathogenesis of numerous inflammatory processes, so we decided to investigate the association between STAT4 gene polymorphisms (rs10181656, rs7574865, rs7601754, and rs10168266) and age-related macular degeneration." (PMID 38275379, 2023).
allergic asthma (2 papers, 2011 to 2014). A asthma with a basis in a pathological type I hypersensitivity reaction. "In this study, we examined whether Th1 or Th2 cells are important regulators of tenascin-C in experimental allergic asthma utilizing mice with impaired Th1 (STAT4-/-) or Th2 (STAT6-/-) immunity." (PMID 21205293, 2011). "To test whether Th1 or Th2 cells are important regulators of tenascin-C expression in experimental allergic asthma, we studied the responses of mice with impaired Th1 (STAT4-/-) or Th2 (STAT6-/-) immunity." (PMID 21205293, 2011). "Surprisingly, however, the OVA-challenged STAT4-/- mice showed no increase in tenascin-C mRNA production after allergen challenge, suggesting that STAT4 is an important regulator of tenascin-C in acute allergic asthma." (PMID 21205293, 2011).
cervical cancer (2 papers, 2020 to 2023). A primary or metastatic malignant neoplasm involving the cervix. "The reason for the high expression of STAT4 in cervical cancer being associated with a poor response is something that should be investigated." (PMID 33076315, 2020). "However, there are minimal preceding reports; therefore, more studies are needed to understand the role of STAT4 in cervical cancer." (PMID 33076315, 2020). "However, the role of STAT4 in cervical cancer has been poorly studied." (PMID 33076315, 2020).